CD4 (CD4 molecule)
Diseases named in the same sentence as CD4 in open-access papers (continued):
Sharing a sentence is not in itself a finding about the gene and the disease.
COVID-19 (continued). "We did not observe significant differences in total CD4+ T cell, CD8+ T cell or B cell frequency in peripheral blood of COVID-19 patients compared to healthy controls, irrespective of disease severity." (PMID 33546489, 2021). "Peripheral CD45RO+ memory CD4+ T cell and CD3-CD19+ B cell frequencies in patients with active or after COVID-19 were numerically, but not significantly increased compared with healthy donors." (PMID 33959123, 2021). "In contrast to the CD4 T cells, we did not observe a correlation between CD38+HLA-DR+ cells and PD-1+ cells in COVID-19 patients, probably suggesting that PD-1 expression on CD8 T cells is more a marker of exhaustion than of activation." (PMID 33777054, 2021). "Based on the 2-sided Kolmogorov-Smirnov test, severe and nonsevere COVID-19 types differed significantly in most laboratory features, except for platelet (PLT), hemoglobin (HGB), CD3, and CD4." (PMID 33714935, 2021). "The guideline was updated one month after the completion of this study (March 2021) and recommended COVID-19 vaccination for PLWHA, regardless of their CD4+ T cell counts." (PMID 34543223, 2021). "For all studies reporting CD3, CD4, and CD8 counts, the standardised mean difference in severe versus non-severe COVID-19 was significantly lower in severe disease (P < 0.00001 for all three)." (PMID 35965490, 2021). "Consistent with previous research, we also found that CD4 + and CD8 + T cells were significantly decreased in non-surviving COVID-19 patients in comparison to survivors." (PMID 33664741, 2021). "While circulating SARS-CoV-2 S-targeted and non-S-targeted CD4+ cells were identified in 100% of COVID-19 convalescents, SARS-CoV-2-specific CD8+ T cell responses were only observed in 70% of COVID-19 convalescent patients." (PMID 33672450, 2021). "In the COVID-19 patients who did not require a ventilator, ACE2 was expressed in CD14 monocytes, CD4 memory and naive T cells, and dendritic cells; TMPRSS2 was expressed in several immune cells." (PMID 34578338, 2021). "A recent report demonstrated the secretion of Granzyme B by CD4+ and CD8+ T cells isolated from COVID-19 patients although without the co-expression of CD107 and TNFα, suggesting an exhaustion state of these cytotoxic cells." (PMID 34436366, 2021). "Peripheral blood total counts of T cells, CD4+, and CD8+ T cells were significantly lower in ICU patients than non-ICU cases with COVID-19 and counts were negatively correlated with patient survival." (PMID 33643932, 2021). "Eighteen KTRs with active COVID-19 infection had lower total lymphocytes and lower circulating memory CD4+ and CD8+ T cells compared with 36 matched KTRs without COVID-19." (PMID 34578460, 2021). "Peripheral lymphopenia affecting CD4 and CD8 T cells was a striking feature of severe COVID-19 compared with non-severe disease." (PMID 35965490, 2021). "As a rule, regardless of COVID-19 severity, the activation of CD8 T cells is more pronounced than that of CD4 T cells." (PMID 34603758, 2021). "Unlike CD4+ T cells, the number of CD8+ T cells was increased 1.6- and 1.3-fold in severe and critical COVID-19, respectively, in comparison with patients with mild disease." (PMID 34122423, 2021). "Increased expression of PD-1 in the absence of an increased expression of Tim-3 on CD3+CD4+ and CD3+CD8+ cells suggests potential reversibility of ongoing immune paralysis in patients with the most severe course of COVID-19." (PMID 33937096, 2021). "Our analysis cannot provide evidence of the role of HIV related parameters on outcomes of COVID-19 related hospitalization, as we did not have details of the ART history, plasma HIV-1 RNA load, CD4 cell count, and history of HIV related disease." (PMID 33095853, 2021). "The total numbers of circulating CD45+ cells, CD4+ T-cells and CD8+ T-cells were not different between individuals who had other respiratory infections and those who had COVID-19 at either 1–3 months or 6–9 months post-symptom onset." (PMID 34835045, 2021).
COVID-19 (continued). "Tα1 appeared to have no beneficial effect neither on the recovery of CD4+ and CD8+ T cell counts nor on the virus clearance during the convalescence stage of COVID-19." (PMID 34149679, 2021). "Findings have illustrated a negative correlation between CD4/CD8 T-cell ratio and the severity of frailty in the elderly in viral infection, however, the performance of these cells in COVID-19 needs to be explored." (PMID 34943875, 2021). "The CD4+/CD8+ ratio and proportions of innate-like T cells were comparable between non-severe COVID-19 patients and healthy controls." (PMID 35095917, 2021). "Increased frequencies of virus-specific CD4+ and CD8+ T cells were found in SARS-CoV-2 positive patients with OTD compared with those with severe COVID-19 and with SARS-CoV-2 negative OTD individuals." (PMID 34858405, 2021). "Similar percentages of CD4+ T cells expressing CCR4, CCR6, CD161, CXCR3, TBET, and GATA3 were found among healthy donors and pregnant women with or without COVID-19." (PMID 34326336, 2021). "But in contrast to CD4+ T cells, the CD8+ immune responses of both unexposed cohorts did not significantly differ from patients with COVID-19." (PMID 34228322, 2021). "Both memory CD4+ and CD8+ T-lymphocyte frequencies were higher in non-hospitalized COVID-19 patients whereas memory B-lymphocyte frequencies were higher in hospitalized patients." (PMID 35046961, 2021). "The overall frequencies of CX3CR1+ CD4+ and CD8+ T cells were not increased in MIS-C compared to pediatric COVID-19." (PMID 33653907, 2021). "Males that deteriorated from COVID-19 had positive correlations between glutamate abundance and CD8+ T cell proportion in T cells and a negative correlation with CD4+ T cell proportion in T cells." (PMID 34230210, 2021). "A recent study shows that in mild COVID-19, SARS-CoV-2 induces strong responses of CD8 T cells, characterized by the expression of granzyme A, B, and perforin, without obvious responses of CD4 T cells." (PMID 33907514, 2021). "The analysis did not confirm correlations with the CD4 subset, highlighting the link with CD8 senescence and exhaustion phenotypes, which are specific immune dysfunctions of COVID-19." (PMID 34959594, 2021). "Our previous studies revealed that total lymphocytes, CD3+, CD4+, and CD8+ T cells were dramatically lower among patients with severe COVID-19 than among non-severe patients at admission." (PMID 34938296, 2021). "Among COVID-19 patients, we observed the trend of increased Treg-CTLA4 and CD4-GZMB, and decreased CD4-Naïve and CD4-GZMK in severe over non-severe groups." (PMID 35095917, 2021). "In the study, we showed that in the group of COVID-19(−) virus there were the strongest positive correlations RE-LYMP with CD38 and HLA-DR markers in both CD4 and CD8+ cells without correlations with markers CD25 and CD45RO." (PMID 33419040, 2021). "Lymphocytopenia affected different subpopulations of lymphocytes, including CD4+ and CD8+ T cells, NK and NKT cells, but not B cells subsets, as their relative percentage within lymphocytes increased in severe COVID-19 patients." (PMID 33692788, 2021). "While CD4:CD8 and TH1:TH2 ratios were not significantly skewed in COVID-19 compared to controls, a significantly lower M1:M2 ratio was observed in COVID-19 [median 0.17 (mean 0.32) in COVID-19 compared to 0.76 (1.34) in controls, p=0.001]." (PMID 34966385, 2021). "In severe or fatal COVID-19 patients more than 22 days post-symptom onset, an extended absence of SARS-CoV-2-specific CD4+ T cells was reported." (PMID 34696342, 2021). "In contrast, CD4+ and CD8+ Tcm cell, as well as Tte frequency was unchanged in COVID-19 patients irrespective of the course of disease." (PMID 33546489, 2021). "In the present study of patients with COVID-19, the baseline median values of CD3+, CD4+, and CD8+ counts were lower than the lower limit of the normal range." (PMID 33125396, 2020).
COVID-19 (continued). "The individual contributions of CD4 and CD8 T cell responses in COVID-19 disease progression is not known." (PMID 33262067, 2020). "The counts of T cells including CD3 T cells, CD4 T cells and CD8 T cells decreased in non-survivors of COVID-19 in the present study." (PMID 32737627, 2020). "35% of acute cases and 73% of non-hospitalized convalescent COVID-19 cases fulfilled the ADIM 3 group criteria of successful SARS-CoV-2-specific neutralizing antibody, CD4+ T cell, and CD8+ T cell responses." (PMID 33010815, 2020). "This increase in both CD4+ and CD8+ CD38+HLA-DR+ T cells preceded resolution of clinical symptoms in a non-severe, recovered, COVID-19 patient." (PMID 32591408, 2020). "Our data showed that the proportions of IFNγ+CD4+ and IFNγ+CD8+ T cells increased and inversely correlated with SARS-CoV-2 viral load in surviving hypertensive patients with severe COVID-19 but not in the fatal cases." (PMID 33362779, 2020). "Labs showed pancytopenia, hyponatremia, mildly elevated total and direct bilirubin, transaminitis, CD-4 count 96/mcL, HIV viral load undetectable and COVID-19 polymerase chain reaction (PCR) negative." (PMID 33364090, 2020). "Circulating CD4 and CD8 T cells, NK cells, and proinflammatory cytokines are significantly lower in COVID-19 HD patients, compared to non-HD COVID-19 individuals." (PMID 32793615, 2020). "The means of CD4+ and CD8+ T cells in the 5,218 hypertensive patients without COVID-19 were 872 (SD = 311) and 483 (SD = 216) cells/μl." (PMID 33362779, 2020). "The proportion of PD-1+ memory CD4+ T cells, but not of PD-1+ CD8+ T cells, in moderate or severe COVID-19 correlated with donor age." (PMID 32669287, 2020). "Given that this last phase of pseudotime 1 (i.e. UMAP clusters 3 and 6) is dominated by CD4+ T-cells from severe patients, these results collectively support that FOXP3-mediated negative feedback on T-cell activation is defective in COVID-19 patients." (PMID 33178221, 2020). "In the present study, we demonstrated the increasing trend of the percentages of CD4 and CD8 immune cells, as well as the decreasing trend accompanied by the recovery of the COVID-19 patients in the family cluster and non-family cluster." (PMID 33328533, 2020). "Consistently, TCR sharing analysis among different T cell subsets revealed much more active interchange between different CD4+ T cell subsets and cycling T cells but not among CD8+ T cell subsets during severe COVID-19." (PMID 33101705, 2020). "Interestingly, older COVID-19 patients tended to also have smaller populations of the “naive” T cells, which could recognize the new SARS-CoV-2 virus and then develop into mature CD8+ killer T cells and CD4+ T helpers, which otherwise mounts a coordinated attack against SARS-CoV-2." (PMID 33277465, 2020). "The frequency of plasmablasts in individuals with severe COVID-19 did not correlate with age, days since onset of symptoms or the presence of comorbidities, APACHE III score nor frequency of CD4+ cTfh cells." (PMID 32669287, 2020). "CD4+ Th1 lymphocytes co-expressing IFNγ and GM-CSF are reported almost exclusively in ICU patients with COVID-19, with relative absence of these cells in non-ICU patients and healthy controls." (PMID 32848776, 2020). "In our earlier work, we measured CD4+ and CD8+ T cell responses in a cohort of average, non-hospitalized cases of COVID-19 during the convalescent phase as a first benchmark of ADIMs to SARS-CoV-2." (PMID 33010815, 2020). "The frequency of PD-1+ memory CD4+ T cells (p=0.0084), but not CD8+ T cells, was also higher in the severe COVID-19+ group compared to the HD group." (PMID 32669287, 2020). "Therefore, CD4+ and CD8+ T cell responses to SARS-CoV-2 antigens were compared between participants with and without COVID-19." (PMID 41251472, 2025). "We next determined whether the ten highly conserved non-Spike antigens are targeted by CD4+ and CD8+ T cells from “naturally protected” unvaccinated COVID-19 patients." (PMID 40894020, 2025).
COVID-19 (continued). "We observed a significantly higher expression of TIM-3 on CD4+ and CD8+ cells in all COVID-19 groups than in healthy controls; however, only a non-significant trend toward a higher expression of TIM-3 on CD4+ and CD8+ cells was observed in non-survivors compared to survivors." (PMID 40005306, 2025). "Furthermore, IFNG (IFN-γ gene) was specifically increased in the Malawian cohort in CD4 and CD8 T cells versus HLCA COVID-19 and non-LRTD groups." (PMID 39567718, 2024). "Taken together, these results demonstrate that, like SARS-CoV-2-specific CD4+ T cells, an overall higher magnitude of CCCs/SARS-CoV-2 cross-reactive CD8+ T-cell responses were present in asymptomatic COVID-19 patients who never presented any COVID-19 symptoms, despite being infected." (PMID 38605956, 2024). "We designed a multi-epitope-based coronavirus vaccine that incorporated B, CD4+, and CD8+ T- cell epitopes conserved among all known SARS-CoV-2 VOCs and selectively recognized by CD8+ and CD4+ T-cells from asymptomatic COVID-19 patients irrespective of VOC infection." (PMID 38318166, 2024). "In COVID-19-related AIDP, one small histological series demonstrated no viral invasion but primarily CD68+++ histiocytes, often accompanied by cytotoxic CD8++ T-cells and less frequently helper CD4+ T cells." (PMID 37712090, 2023). "Additionally, the CD4+ FOXP3+ Tregs of the lung and PBMC showed a rising trend on day five after infection in the nonhuman model of COVID-19 pathogenesis." (PMID 36992283, 2023). "However, severe COVID-19 patients had more CTLA-4+ CD62L+ cells (p=0.01) and PD-1+ CD62L+ cells (p=0.049) in the total CD4+ population compared to non-severe patients." (PMID 36817450, 2023). "However, there are no reports on CD4+ and CD8+T cells regarding progression and mortality for COVID-19 patients who treated with Nirmatrelvir." (PMID 37799722, 2023). "Whereas COVID-19 vaccines have been deemed safe for PLWH with no specific allergies reported so far, nonetheless, low CD4+ cell counts may reduce vaccine immunity." (PMID 37288215, 2023). "Reports have suggested that COVID-19 vaccination may have negative effects on PLWH, including HIV reservoir rebound and decreased CD4 counts." (PMID 38140668, 2023). "Within the CD4+ T cell populations, no statistical differences on IFN-γ release were found for naïve effector memory (EM) and terminally differentiated effector memory (EMRA) between vaccinated and COVID-19 recovered children." (PMID 38005968, 2023). "We observed that the frequencies of SARS-CoV-2 spike-specific CD4+ and CD8+ T cells were not significantly different between older and younger adults after 2 doses of COVID-19 mRNA vaccine, and that these responses were enhanced similarly by a third vaccine dose regardless of age." (PMID 38035132, 2023). "With the help of the CIBERSORT platform, it was observed that in COVID-19-positive patients, Plasma Cells, Activated CD4 Memory T Cells, CD8 T Cells, both Activated and Resting Dendritic Cells, M0 Macrophages, and Neutrophils were statistically different from that in COVID-19-negative patients." (PMID 37065165, 2023). "Indeed, emerging evidence has shown that patients with long COVID-19 are characterized by higher and more persistent levels of SARS-CoV2 antigen-specific follicular CD4+ T and T helper cells than patients with COVID-19 without sequelae." (PMID 36836568, 2023). "Finally, classical αβ CD4+ and CD8+ T cell activation followed a similar trajectory in pregnant and nonpregnant women with COVID-19." (PMID 37036008, 2023). "Interestingly, Tfh cells’ frequency in COVID-19 was lowered, regardless of COVID-19 severity, but within central memory Th cells, a lower level of CXCR5-expressing CD4+ T cells was found in patients with severe COVID-19 vs. patients with moderate COVID-19." (PMID 36146713, 2022).
COVID-19 (continued). "We also observed a significant difference at the early time point in the proliferative CD4+ and CD8+ T-cell responses between post-COVID-19 patients with pneumonia or mild symptoms (but not between either the post-COVID-19 patient group or vaccinated subjects)." (PMID 35744768, 2022). "In breakthrough COVID-19 infections, characterized by mild clinical course, we observed increased percentage of in-vitro NET-osis, higher CD4+ CD45RO+ and CD8+ CD45RO+ T cells healthy or mild-COVID-19 not-vaccinated patients, reduced by 24 h of treatment with ACE inhibitor ramipril." (PMID 35508575, 2022). "Interestingly, a great increase in plasma levels of IL-18, a cytokine involved in the induction of the CD4+ TH1 profile, was observed in children with severe but not in those with non-severe COVID-19 (p<0.0001)." (PMID 35663467, 2022). "However, CD4 T cell, CD8 T cell, and total T-cell numbers were not remarkably changed in severe patients compared to mild COVID-19 patients (p > 0.05)." (PMID 36403042, 2022). "Interestingly, while circulating CD4+ T cells against spike epitopes directly correlated with RBD- and spike-specific IgG in pediatric COVID-19, this was not the case for MIS-C." (PMID 35044955, 2022). "All included studies for CD4 T-cells (six studies) reported decreased counts in the non-survivors relative to survivors (SMD = −0.99 to −0.03), for the pairwise comparison between COVID-19 survivors and non-survivors." (PMID 35572964, 2022). "Additionally, NKG2A was upregulated on peripheral blood CD4+ and not on CD8+ T cells in severe COVID-19 patients, compared with mild and moderate diseases." (PMID 35432324, 2022). "It has been shown that frequency of multi-functional CD4+ T cells and non-exhausted CD8+ T cells were significantly lower in severe COVID-19 cases compared with mild group and healthy controls, whereas the number of non-functional subsets significantly increased." (PMID 36499448, 2022). "CD4+ T cell responses to the spike MP correlated with both RBD IgG titers (r = 0.6; P = 0.007) and spike IgG titers (r = 0.75; P = 0.0003) in participants with convalescent COVID-19 but not MIS-C." (PMID 35044955, 2022). "It has been shown that humoral immunity is not vital in clearing acute COVID-19 if there are sufficient amounts of CD8+ T cells, and that the major role of CD4+ T cells in the clearance of COVID-19 is to instruct humoral immunity with a much lighter role in amplifying cellular immunity." (PMID 35955740, 2022). "To determine the effect of MIS-C on memory CD4+ T cell subsets, we assessed the absolute numbers of CD4+ T cell subsets by flow cytometry in MIS-C children and compared them with acute COVID-19, other infectious and non-infectious diseases and healthy control children." (PMID 36322537, 2022). "Both CD4+ and CD8+ T cells, which were depleted in MIS-C but not in COVID-19, also increased during recovery from MIS-C and remained unchanged during recovery from COVID-19." (PMID 35275061, 2022). "In addition, on 5 days post-infected (dpi), the CD4+ FOXP3+ Tregs of lung and PBMC exhibited an increasing trend in the nonhuman primate model of COVID-19 progression." (PMID 35874688, 2022). "As compared with controls, SARS-CoV-2-infected adults with less severe COVID-19 who were treated as outpatients had no reduction in ILCs, but 1.44-fold fewer CD16+ NK cells (95% CI: 1.93–1.07; p = 0.018), and 1.26-fold higher CD4+ T cells (95% CI: 1.06–1.5; p = 9.59 x 10–3)." (PMID 35275061, 2022). "MicroBeads selected CD4+ T cells, CD8+ T cells, and CD14+ monocytes from PBMCs were treated with plasma exosomes from early-stage COVID-19 patients and non-COVID donors for 16 h at 37 °C, followed by flow cytometry for expression of TLR3, TLR7, TLR8, and TLR9 gating on live cells." (PMID 36526691, 2022). "However, upon considering a broader spectrum of TFH cells regardless of ICOS expression, CD4+, CXCR5+, and PD-1+ TFH were most abundant in COVID-19 patients with mild disease." (PMID 33361110, 2021).